FLI1 (Fli-1 proto-oncogene, ETS transcription factor)
Diseases named in the same sentence as FLI1 in open-access papers (continued):
Sharing a sentence is not in itself a finding about the gene and the disease.
Ewing sarcoma (continued). "Although, in hpMSCs, overexpression of EWSR1::FLI1 remodels the chromatin landscape by redistributing H3K27me3, in Ewing sarcoma cell lines, depletion of KDM6B—but not KDM6A—exerts its main effects partly by restoring H3K27me3 levels at enhancers." (PMID 41085408, 2025). "When diagnosing Ewing sarcoma of the lung, the central role lies in distinguishing the histological findings of ES from its mimics, as well as identifying essential IHC markers such as CD99, FLI1, and NKX2.2." (PMID 41278275, 2025). "On the other hand, FLI-1 expression is more characteristic of Ewing sarcoma, while the absence of CD61 in immunohistochemical studies also questions the diagnosis of AMKL." (PMID 40565358, 2025). "To shed light on whether KDM6A and KDM6B demethylases are involved in H3K27me3 to H3K27ac switches in enhancers regulated by EWSR1::FLI1, we carried out ChIP-seq for KDM6A, KDM6B, and EWSR1::FLI1 in the Ewing sarcoma cell line A-673." (PMID 41085408, 2025). "Finally, we apply the power of this assay to determine the function of the EWSR1::FLI1 fusion oncogene and its transcriptional target SOX6 as plasticity factors that enhance the adaptive capacity of metastatic Ewing sarcoma." (PMID 40501949, 2025). "This index case confirms that the expression of FLI-1 in hematolymphoid neoplasms has not been sufficiently explored, specifically in plasmacytic or high-grade lesions that mimic Ewing’s sarcoma." (PMID 38280044, 2024). "Altered EWS::FLI1 dependent transcription is unlikely to explain all the changes that are important in promoting the more aggressive phenotype of Ewing sarcoma in patients lacking STAG2." (PMID 39487368, 2024). "A translocation in Ewing sarcoma, the second most common malignant bone tumour, most commonly between chromosomes 11 and 22, often results in a fusion between the 5′ region of the EWS gene and the 3′ region of FLI1." (PMID 38542080, 2024). "Although EWSR1::FLI1 is indispensable to maintain Ewing sarcoma growth, increased expression of EWSR1::FLI1 is also not tolerated as it causes cell growth arrest and cell death." (PMID 36672331, 2023). "Ewing sarcomas (ES) are rare small round cell sarcomas often affecting children and characterized by gene fusions involving one member of the FET family of genes (usually EWSR1) and a member of the ETS family of transcription factors (usually FLI1 or ERG)." (PMID 37372318, 2023). "This is an accepted approach to identify EWS–FLI-binding sites because wild-type FLI1 typically is not expressed in Ewing sarcoma cells." (PMID 36658220, 2023). "In Ewing sarcoma cells, EWS/FLI1 binds to the promoter of FOXO1 and suppresses its expression." (PMID 37894854, 2023). "We found that in Ewing sarcoma cells, MS1360 interacts with EWSR1::FLI1." (PMID 36793594, 2023). "For treatment of Ewing sarcoma xenografts we chose YK-4–279, described as inhibitor of EWS::FLI1/RNA helicase A interactions and microtubule polymerization, which has been reported to induce apoptosis in Ewing sarcoma cells and lead to growth reduction in a mouse xenograft model." (PMID 37202469, 2023). "By using the extensively studied A673/TR/shEF cell line, we showed that CD44 was dramatically upregulated upon EWSR1::FLI1 downregulation (that is, in the EWSR1::FLI1low phenotype), suggesting that CD44 is repressed by EWSR1::FLI1 in EWSR1::FLI1high Ewing sarcoma cells." (PMID 37511533, 2023). "The mechanism potentially involved in the negative regulation of CD44 expression in Ewing sarcoma under these conditions remains unknown, but it clearly correlates with the expression levels of EWSR1::FLI1 protein." (PMID 37511533, 2023). "Image-guided Tru-Cut biopsy confirmed Ewing’s sarcoma, positive for ESW/FLI1 translocation." (PMID 36869935, 2023). "Ewing sarcoma is driven by chromosomal rearrangements that create fusion proteins consisting of the ntEWS and the C-terminus of an ETS family transcription factor such as FLI1 or ERG." (PMID 37956771, 2023).
Ewing sarcoma (continued). "This has led to the concept that Ewing sarcomas adhere to the “Goldilocks” principle, wherein EWS/FLI1 must be maintained at precisely balanced levels: an excess of the fusion protein proves toxic, while insufficient levels fail to sustain malignant properties." (PMID 37894854, 2023). "In Ewing sarcoma cells, the fusion of EWS RNA binding protein 1 (EWSR1) and Friend leukemia integration 1 transcription factor (FLI1) EWS-FLI1 can increase transcription, replication stress and R-loop formation and lead to blocked BRCA1-mediated repair after DNA damage." (PMID 36750826, 2023). "These hypotheses remain speculative, but EWS::FLI1-dependent heterogeneity in immune suppressive and immune activating gene expression may represent an important dimension of how the TME and Ewing sarcoma reciprocally interact." (PMID 36505823, 2022). "Staining of zebrafish tumors with antibodies against FLI1 showed that cells have different expression level of EWSR1-FLI1, consistent with recent reports of cell-to-cell heterogeneity which affects proliferative and migratory potential of Ewing sarcoma cells." (PMID 35285802, 2022). "An attractive hypothesis may be that intratumoral heterogeneity in Ewing sarcoma and differences in EWS::FLI1 activity arise due to distinct cells of origin, or transformation of the same cell of origin but at different developmental time points or contexts." (PMID 36505823, 2022). "Immunosuppressive myeloid derived suppressor cells (MDSCs) have also been identified in Ewing sarcoma patients and may play a role in tumor progression, particularly in the context of EWS::FLI1 “low” cell states." (PMID 36505823, 2022). "While EWS::FLI1 is the major driver of Ewing sarcoma, EWS::FLI1 has been difficult to target." (PMID 36533189, 2022). "Ewing sarcoma is characterized by translocation of chromosomes 22 and 11, resulting in fusion of the corresponding EWS gene and FLI1 gene, thus expressing the fusion gene EWS-FLI1." (PMID 35680570, 2022). "There is growing evidence that hypoxia alters Ewing sarcoma cell state to support metastatic phenotypes, and this may involve modulation of EWS::FLI1 activity." (PMID 36505823, 2022). "While mesenchymal stem cells are a likely Ewing sarcoma cell of origin, the exact subset of these cells and their state when EWSR1/FLI1 forms is unknown." (PMID 34409300, 2021). "A recurrent chromosomal translocation found in the majority of Ewing sarcoma fuses the Ewing sarcoma breakpoint region 1 or RNA‐binding protein EWS (EWSR1) and Friend leukemia integration 1 transcription factor (FLI1) genes generating an EWS–FLI1 fusion protein." (PMID 34060252, 2021). "In contrast to Ewing’s sarcoma, mesenchymal CHS lacks FLI-1." (PMID 34069269, 2021). "Ewing Sarcoma pathogenesis is driven by EWS/Ets, most commonly EWS/Fli1, fusion oncoproteins." (PMID 32577157, 2020). "The main known carcinogenic event in Ewing sarcoma is somatic chromosomal translocation that occurs most commonly between chromosomes 11 and 22 and results in a fusion between the 5′ region of the EWS gene and the 3′ region of the ETS family gene FLI1." (PMID 32714929, 2020). "Ewing sarcoma is an aggressive cancer of the bone and soft tissues resulting from the fusion of Ewing sarcoma RNA Binding Protein 1 (EWSR1) to Friend leukemia integration 1 transcription factor (FLI1) (85%) or E-twenty-six-related (ETS-related) gene (ERG) (15%)." (PMID 32290418, 2020). "Further understanding of such mechanisms should help illuminate the molecular basis of metastatic propensity in Ewing sarcoma, as well as present new approaches to metastasis inhibition, including attenuation of the high metastatic potency of cells with low EWS/Fli1 expression." (PMID 33196691, 2020). "Ewing sarcoma is a cancer of bone and soft tissue in children that is characterized by a chromosomal translocation generating a fusion between EWS and an Ets family transcription factor, most commonly FLI1." (PMID 33147457, 2020).
Ewing sarcoma (continued). "Molecularly, it is characterized by a chromosomal translocation generating a driver fusion gene between the gene EWSR1 (Ewing Sarcoma Breakpoint Region 1) and one gene from the E26 transformation-specific or E-twenty-six (ETS) family (FLI1 in most of the cases), with few other genomic alterations." (PMID 32225029, 2020). "Inspection of individual genes of interest revealed that KDM5A and PHF2 each positively control the expression of Ets1 and MCAM, genes belonging to a metastasis-promoting pathway recently identified in Ewing sarcoma by our group, and negatively regulated by EWS/Fli1." (PMID 33196691, 2020). "FUS is highly related to EWSR1, and both are members of the FET (FUS/TLS, EWS, and TAF15) family of RNA binding proteins, while FLI1 and its related genes are members of the ETS family of DNA binding proteins, and together the “FET-ETS” fusions represent nearly all cases of Ewing sarcoma." (PMID 33488267, 2020). "The positive staining for Sox9 along with negative staining for FLI-1 aids in distinguishing MC from Ewing sarcoma." (PMID 30909775, 2019). "Inversely, some studies have shown that EWS/FLI1 inhibits β-catenin dependent transcription through a direct interaction between EWS/FLI1 and the transcription factor LEF1, inhibiting the interaction between β-catenin and LEF1 in Ewing sarcoma-cell lines." (PMID 31370265, 2019). "The canonical EWSR1-FLI1 fusion was found in all Ewing sarcoma models profiled with RNA-seq (NCH-EWS-1 was not profiled), and CHLA-258 contained an additional FLI1 fusion partner: RP11-9L18.2." (PMID 31693904, 2019). "In contrast to osteosarcoma, Ewing sarcoma is characterized by a chromosomal translocation between the EWSR1 and FLI1 genes in 90% of cases, or by the fusion of EWSR1 with other transcription factors of the E26 Transformation-Specific (ETS) gene family in 10% of cases." (PMID 31370265, 2019). "EWS-FLI-1 is a hybrid transcript that results from a translocation event involving EWS and FLI1, and translocation events such as this are present in nearly all Ewing sarcoma cases and are believed to drive the disease." (PMID 31616462, 2019). "Ewing Sarcoma is driven by transcription factor fusion oncoproteins, most commonly EWS/Fli1." (PMID 30237855, 2018). "Ewing sarcoma (ES) cells are characterized by translocations involving the EWS gene from chromosome 22 and a member of the ETS family of transcription factors, most commonly the FLI1 gene on chromosome 11." (PMID 29371919, 2017). "We hypothesized that EWS/Fli1-induced miRs would include candidate pro-oncogenic miRs, while EWS/Fli1-repressed miRs would include candidate anti-oncogenic miRs in Ewing Sarcoma." (PMID 28542597, 2017). "FLI-1 has been described as a useful marker for Ewing sarcoma, particularly when hematolymphoid markers are negative." (PMID 28439237, 2017). "Biologically, Ewing sarcoma is characterized by recurrent balanced translocations involving the EWSR1 gene and a member of the ETS family of transcription factors, most commonly FLI-1." (PMID 28115942, 2016). "The EWS-FLI1 fusion gene produced from a translocation of chromosomes 11 and 22 results in the juxtaposition of the FLI1 transcription activator next to the EWS gene in Ewing sarcoma." (PMID 27649156, 2016). "This relationship between EWS/FLI1 and CCK was confirmed in Ewing sarcoma cells." (PMID 26258070, 2015). "Ewing sarcoma is a cancer of bone and soft tissue and is characterized by chromosomal translocations involving EWS gene and transcription factors of the ETS family (ERG, FEV, FLI1, ETV1 and E1AF)." (PMID 25925574, 2015). "Ewing sarcoma is a cancer of bone and soft tissue in children that is characterized by a chromosomal translocation involving EWS and an Ets family transcription factor, most commonly FLI-1." (PMID 26807198, 2015). "Because the wild type FLI1 protein is not expressed in Ewing tumors, EWS/FLI1 binding was assayed with an antibody that recognizes the endogenous FLI1 peptide sequence." (PMID 26337082, 2015).
Ewing sarcoma (continued). "In the case of Ewing sarcoma, EWS/FLI1 is an important component of the super-enhancer machinery." (PMID 26337082, 2015). "The primary known oncogenic event in Ewing sarcoma is a somatic chromosomal translocation, most commonly between chromosomes 11 and 22, which results in a fusion between the 5′ region of the EWS gene and the 3′ region of the ETS family gene, FLI1." (PMID 26337082, 2015). "EWS/FLI1 binds to the FOXO1 promoter and represses its expression in Ewing sarcoma cells." (PMID 26258070, 2015). "One study, examining Ewing Sarcoma initiation in pediatric MSCs, identified miR-145 as an EWS/Fli1-repressed miR, and miR-145 repression, in turn, as a means to augment expression of EWS/Fli1 itself, as well as expression of the stemness-associated transcription factor Sox2." (PMID 23543617, 2013). "In the current study, we found that the fusion mRNA could be detected in MVs from not only Ewing sarcoma cells (both type 1 and type 2 fusion of EWS/Fli-1), but also clear cell sarcoma cells which have another fusion gene (EWS/ATF-1)." (PMID 24124617, 2013). "However a case has been described of a patient, in whom two separate Ewing sarcoma/PNET tumours arose after a 56 month remission interval, initially involving a EWS/ERG fusion transcript followed by a EWS/FLI1 fusion." (PMID 22587874, 2012). "Reexpression of CAV1 or E-cadherin in CAV1 knockdown Ewing's sarcoma cells rescued the oncogenic phenotype of the original Ewing's sarcoma cells, showing that the CAV1/Snail/E-cadherin pathway plays a central role in the expression of the oncogenic transformation functions of EWS/FLI-1." (PMID 21471610, 2011). "Ewing sarcoma family of tumors (ESFTs), which includes Ewing sarcoma and primitive neuroectodermal tumors (PNETs), is a group of aggressive malignant neoplasms characterized by small round blue cells and fusion of the ​​​​​​EWSR1 gene with other genes such as FLI1 and ERG." (PMID 40416106, 2025). "Mimicking Ewing sarcoma in mice has been challenging, however, a recent mouse model showed that while EWSR1::FLI1 may be sufficient for tumorigenesis, subsequent YAP1 activation induced by IGF1 signalling may be required for the activation of TEAD driven transcription and metastatic progression." (PMID 40442778, 2025). "Resulting tumors were confirmed to be Ewing sarcoma with positive IHC staining for CD99, a membrane protein expressed uniformly in Ewing tumors, and nuclear staining of NK homeobox 2 (NKX2.2), a transcription factor upregulated by EWSR1::FLI1 fusion oncoprotein." (PMID 40858520, 2025). "Moreover, when we treated Ewing sarcoma cells with the KDM6A/KDM6B demethylase inhibitor GSK-J4, we found that the expression of EWSR1::FLI1-activated targets decreased strongly in those targets containing only KDM6B, suggesting that GSK-J4 phenocopies expression changes induced by KDM6B deletion." (PMID 41085408, 2025). "While EWS/Fli1 expression is inarguably essential to the survival of Ewing sarcoma cells, emerging experimental and clinical evidence suggests that these tumors have significant intra-tumoral transcriptional heterogeneity, characterized by the heterogenous activation of EWS/Fli1." (PMID 38875295, 2024). "While these distinctions between EWS/FLI1 high and low states are somewhat simplified and may not encompass the full spectrum of fusion protein activity observed in Ewing sarcoma cells, they provide a fundamental framework for this review." (PMID 37894854, 2023). "In addition, neoplastic cells shared characteristics of conventional Ewing Sarcoma, with diffuse and strong membranous expression of CD99, nuclear expression of NKX2.2, with varying degree of nuclear positivity for FLI1." (PMID 37518334, 2023). "Thus, it is important to know what specific CD44 isoforms are present upon EWSR1::FLI1 knockdown, as this may be relevant to understanding the role of CD44 in Ewing sarcoma." (PMID 37511533, 2023).
Ewing sarcoma (continued). "While the specific mechanism by which Thiostrepton induces the down-regulation of EWS/FLI1 was not investigated, these findings suggest that this drug may exhibit higher effectiveness in Ewing sarcoma tumors compared to other types of tumors." (PMID 37894854, 2023). "Steroid-dependent translocation of EWSR1::FLI1 and glucocorticoid receptor into nuclei leads to EWSR1::FLI1 binding to the glucocorticoid receptor to enhance glucocorticoid receptor-mediated oncogenic transcription to facilitate Ewing sarcoma growth and migration." (PMID 36672331, 2023). "Indeed, in Ewing’s sarcoma cells, analysis of the PARP1 promoter showed its up-regulation in response to DNA damage, and this is carried out by ETS transcription factors, Ets-1 and Fli1." (PMID 37686260, 2023). "While the exact Ewing sarcoma cell or cells of origin is still an enigma, studies have shown that both neural crest stem cells (NCSCs) and mesenchymal stem cells (MSCs) tolerate EWS::FLI1 expression and lead to increased Ewing-like gene expression and morphology." (PMID 36505823, 2022). "Therefore, in addition to Ewing sarcoma, targeted inhibition of OTUD7A may be relevant for other cancers dependent on FLI1 for proliferation, such as leukemia and kidney cancer." (PMID 34060252, 2021). "Notably, while EWS/Fli1 imposes positive regulatory control over some pro-metastatic genes and pathways (eg: EZH2 and PPP1R1A), multiple studies indicate that, on balance, EWS/Fli1 exerts a repressive effect on important metastatic properties in Ewing sarcoma." (PMID 33196691, 2020). "Having shown that KDM5A and PHF2 promote metastatic properties in Ewing sarcoma, and exert effects on metastasis in opposition to those of EWS/Fli1, we wondered whether inhibition of KDM5A or/and PHF2 could impair the biological properties of more metastatically potent EWS/Fli1low cells." (PMID 33196691, 2020). "Notably, both mouse and human CCS cells showed reduced cell growth by JQ1 treatment in vitro, whereas the effect was not obvious in Ewing sarcomas that harbor EWS/FLI1 fusion oncogene." (PMID 31488818, 2019). "Therefore, based on these functional backgrounds, silencing of co-activator SS18/SSX picked up small amounts of regulated proteins compared to Ewing sarcoma and alveolar rhabdomyosarcoma having either EWS/FLI1 or PAX3/FOXO1 which act as transcriptional factors." (PMID 30680066, 2018). "The consistent, high-level expression of CD99 and the presence of a EWS gene-rearrangement with FLI1, ERG or, in rare cases, other ETS genes are the hallmarks of Ewing sarcoma, and a functional relation exists between the two, although that relation remains unclear." (PMID 29534016, 2018). "Finally, studies in which EWS/FLI1 was overexpressed in animal models suggest that expression of EWS/FLI1 alone is not sufficient to induce Ewing sarcoma." (PMID 27557633, 2016). "Characterization of the EWS-FLI1 fusion sites of 42 pediatric and young adult Ewing sarcoma patients and seven cell lines revealed a clustering in the 5′ region of the EWS-breakpoint cluster region (BCR), in contrast to random distribution of breakpoints in the FLI1-BCR." (PMID 23441188, 2013). "The fact that EWS/FLI1 downregulates LOX in the A673 Ewing sarcoma cell line and that low levels of LOX are a common feature of Ewing sarcoma cells and tumors, suggest that LOX could act as a tumor suppressor in Ewing tumors." (PMID 23750284, 2013). "In this study, we examined whether MVs generated from Ewing sarcoma cells might carry the EWS/Fli-1 fusion mRNA and found, by using both in vitro and in vivo systems, that MVs can indeed contained the Ewing sarcoma-specific EWS/Fli-1 mRNA." (PMID 24124617, 2013). "Ewing tumours (ET), including Ewing's sarcoma and peripheral primitive neuroectodermal tumour, are well characterised at the molecular level by a unique chromosomal rearrangement which fuses the EWS gene to one of two closely related ETS proto-oncogenes, FLI-1 or ERG." (PMID 7524604, 1994).